IFNG (interferon gamma)
Diseases named in the same sentence as IFNG in open-access papers (continued):
Sharing a sentence is not in itself a finding about the gene and the disease.
tumor (continued). "These unique tumour-infiltrating CD4+ T cells expressed the transcription factor BHLHE40, the effector cytokine IFNG, and the chemokine receptor CXCR5." (PMID 32457487, 2021). "Celecoxib in combination with IFNγ reduced the expression of MMP-2, MMP-9, and VEGF-A in tumor and decreased MVD, mediated by the increased amount of CD68+iNOS+ M1 macrophages and by decreased amount of CD68+Arg1+ M2 macrophages in mouse model of LLC." (PMID 34209679, 2021). "The most commonly used approach is intracellular cytokine staining (ICS) focusing on the detection of molecules such as interferon-gamma (IFNγ), tumor necrosis factor (TNF), and interleukin 2 (IL-2), after recognition of tumor-antigens." (PMID 34707600, 2021). "Interestingly, the absence of caspase-1 activity in tumor cells was not only associated with decreased mRNA levels of caspase-1 and downstream cytokines IL-18 and IFNγ, but also with upstream inflammasome sensors or regulators, among which NLRC5 is of particular interest." (PMID 33430344, 2021). "After activation, NK cells secrete cytokines (e.g., IFNγ, TNF) and chemokines (e.g., MIP1α) that modulate the function and trafficking of other immune cells, promoting an inflamed tumor microenvironment." (PMID 34187852, 2021). "M1 macrophages are mainly produced by inducing the interferon gamma (IFN-γ) and lipopolysaccharides (LPS), which have been reported to exert important anti-tumor properties." (PMID 34506209, 2021). "Compared with WT mice, the number of macrophages infiltrating the tumor of IRF3KO mice was significantly reduced, and CD4+ T cells and CD8+IFNγ+ T cells were significantly increased." (PMID 34768716, 2021). "Upon tumor antigen recognition in the context of the MHC, the T cell releases interferon gamma that binds to its receptors on the cancer cell." (PMID 34268109, 2021). "Altogether, the upregulated expression of Ki67, IFNγ, CD25, and CD27 among the CD8 and CD4 T-cell clusters indicate that the large tumors in the PD-1cKO are highly immunogenic with a potential for tumor regression, evident at later time points." (PMID 34912335, 2021). "Both esCAR Tpre and esCAR Tpost cells released similar amounts of IFNγ, granzyme B, and GM-CSF when exposed to CD19+ tumor cells." (PMID 33526841, 2021). "Intriguingly, IFNγ released from CD8+ T cells downregulates the expression of SLC7A11 and SLC3A2, thereby limiting cystine uptake by tumor cells and promoting tumor cell lipid peroxidation and ferroptosis." (PMID 34312372, 2021). "We found that T cell migration to tumor conditioned medium from cells treated with the combination of GSK126 and IFNγ was significantly increased when compared to medium from vehicle treated cells, the trend being additive of the single treatments." (PMID 34336705, 2021). "TNF, IFNγ and CXCL10 levels were significantly increased in plasma of mice with RM-1 tumors compared to tumor naïve mice." (PMID 33786638, 2021). "Among IFNγ targets, the chemokine CXCL10 has been shown to control T-cell recruitment into the tumor environment." (PMID 34220848, 2021). "Tumor-infiltrating CD8+ T cells from the double cKO mice had significantly higher levels of granzyme B expression and increased numbers of IFNγ expressing cells." (PMID 34142056, 2021). "Upon recognition of the tumor antigen, CAR-T cells release pro-inflammatory cytokines including interferon gamma (IFNγ), interleukin (IL)-1, IL-2 receptor alpha (RA), tumor necrosis factor alpha (TNFα), and IL-6 to induce a cytotoxic response." (PMID 33802788, 2021). "IL-17 was found to potentiate the anti-tumor activity of neutrophils by enhancing the production of cytotoxic molecules, including ROS, MPO, TRAIL and IFNγ." (PMID 34572138, 2021). "Stimulation of NK cells with IL-12 leads to secretion of IFNγ and TNF-α, as well as increased levels of chemokines such as MIP-1α, IL-8 and RANTES, further stimulating the infiltration of CD8+ T cells into the tumor." (PMID 34557197, 2021).
tumor (continued). "In addition to T cells, the activation of eosinophils can also normalize tumor blood vessels, but the exact mechanism is unclear, which may be that the TAMs were polarized into an M1-like phenotype through eosinophil-derived IFNγ and TNF signaling, leading to a reduced low VEGF production." (PMID 34476218, 2021). "Disruption of the CBM signalosome complex also results in the acquisition of an anti-tumor effector phenotype by TIL Tregs, i.e., production of IFNγ, and reduced tumor growth." (PMID 34394124, 2021). "For cluster 22, the cells were defined through the expression of CD8+, CD39+, CD223+ (Lag-3), CD62L−, GrzB+, and IFNγ, indicating activated CD8+ T cells capable of tumor killing function." (PMID 34912335, 2021). "Subjects treated with pHIFU + ICI had increased levels of CD8+IFNγ+ T cells, increased ratios of CD8+IFNγ+ to CD3+CD4+FoxP3+ and CD11b+Ly6G+ cells, and decreased CD11chigh cells in their tumours compared with controls." (PMID 34229458, 2021). "This, when paired with anti-PD-L1, increased IFNγ production, CD4+ and CD8+ T cell proliferation, tumor regression, and overall survival." (PMID 34975924, 2021). "CRISPR/Cas9-mediated editing of A2AR rendered CAR T cells resistant to NECA in terms of their capacity to secrete IFNγ, TNF, and MIP1α (CCL3) upon coculture with either OVCAR-3 cells or MCF7 cells, another Lewis Y+ tumor cell line." (PMID 34050151, 2021). "The refined six gene tumor immune signature (IDO1, CXCL10, CXCL9, HLA-DRA, STAT1, IFNG) was carried on a sample of cases representative of the Sema4D HIS subtypes using basic nSolver analysis." (PMID 33776991, 2021). "RT helps trigger the release of tumor antigens, improve presentation of tumor antigens to T cells, and induces an inflammatory response in the TME that results in elevated IFNγ levels and reduced immunosuppression." (PMID 33936058, 2021). "Among them, Th1 cells, characterized by production of IFNγ and TNFα, can optimize CTL activity, and thus promote anti-tumor immunity." (PMID 34794428, 2021). "What is more, there were higher expressions of FCRL3, IFNG, and TRAT1 in recurrent tumor(n = 5) compared with primary tumor(n = 371)." (PMID 34868239, 2021). "NK cell depletion truncated the tumor immunity of HSD, which was found to be mediated by NK-dependent interferon-γ (IFNγ) response." (PMID 34516769, 2021). "At the same time, the DC boost approach reinforced migratory dermal DC subsets to prime gp100-specific CD8+ T cells in tumor-draining LNs that expressed PD-1/TIM-3 and produced interferon γ (IFNγ)/tumor necrosis factor α (TNFα)." (PMID 33408092, 2021). "Orthotopic HCC mice treated with these DCs harbored an elevated number of T lymphocytes, increased levels of IFNγ and decreased levels of IL-10 and TGF-β at tumor sites." (PMID 33435564, 2021). "IL-2 and IFNγ (Interferon) producing CD4 T cells such as Th1 have been shown to play an essential role in the induction and persistence of anti-tumor CD8 T cells." (PMID 33498483, 2021). "Of particular interest, in vivo, we observed an additional role for immune signaling pathways (IFNγ, PD-1, and ZAP70) and myeloid leukocyte activation-migration into the tumor microenvironment (TME) to promote immunogenic cell death." (PMID 33499163, 2021). "Cytotoxicity correlated with upregulation of MHC-I and PD-L1 molecules on anti-PD-1-treated B16F10E-KO tumour cells as compared to isotype-treated B16F10E-KO, which correlated with high production of IFNγ by CD8+ TIL." (PMID 34471106, 2021). "Activation of the PD1/PD-L1/L2 pathway inhibits T cell proliferation and secretion of interferon-gamma (IFN-γ), tumor necrosis factor-alpha (TNF-α), and IL-2, sustaining the immune inhibitory state of the tumor microenvironment." (PMID 34526987, 2021). "Intravenous infusion of IL12IL2DiaNFGMCSF induced tumor‐infiltrating immune cell alterations like IL12IL2GMCSF, with moderate serum IFNγ increment." (PMID 34766145, 2021).
tumor (continued). "However, we could replicate the association of PBRM1 mutation and a non-immunogenic tumor phenotype, which has been caused to be related to the downregulation of IFNγ target genes." (PMID 34215851, 2021). "STAT1 expression is stimulated by IFNγ and leads to the expression of MHC-II at the tumor cells surface which are molecules presenting tumoral antigens to the host immune system." (PMID 33691728, 2021). "Interferon-gamma, INF-γ, a potent cytokine known to modulate tumor immunity and tumoricidal effects, has been shown to be highly elevated in patients with PCa after radiation." (PMID 34638243, 2021). "In gastrointestinal cancer, lymphocytes secrete cytokines, such as interferon gamma (IFN-γ) and TNF-α, thereby controlling tumor growth and improving the prognosis." (PMID 34992504, 2021). "With our functional in vitro studies, we demonstrated that in the presence of immobilized target antigens, CAR T products rich in effector memory T cells secreted higher amounts of IFNγ and IL-2, and induced more potent CAR-specific anti-tumor activity." (PMID 34503109, 2021). "Splenocytes from animals in the CC-SpT-OTI/SnT-OTII OMVs group also secreted the most IFNγ when re-stimulated with OVA257–264 and OVA223–339, which is consistent with efficient antigen presentation and the anti-tumor effects." (PMID 33824314, 2021). "A CD8 T effector gene signature including CD8A, CD8B, EOMES, GZMA, GZMB, IFNG, and PRF1 was established to identify activated T cells and can be used to evaluate the abundance of CTLs in the tumor microenvironment." (PMID 33611641, 2021). "Overexpression in tumor cells of the glycolysis enzyme HK2 suppresses glucose uptake and interferon gamma (IFN-γ) production in tumor-infiltrating lymphocytes (TILs)." (PMID 33922558, 2021). "In common with IFNγ, the ability of type I IFN to promote immune-mediated anti-tumor activity is also through their effects on T cells." (PMID 33842331, 2021). "In pre-treatment tissue samples from mRCC patients with mccRCC, we observed an inflamed tumor microenvironment with enriched expression of genes belonging to both the vascular endothelial growth factor (VEGF) and interferon gamma (IFN-γ) signaling pathways." (PMID 34737281, 2021). "Many cytokines were found to induce PD-L1 expression; however, interferon-gamma (IFN-γ) is the main stimulator along with its IFN-γ and toll-like receptor (TLR) ligands, which also impair the immunity of effector tumor cells." (PMID 34069461, 2021). "Serum concentrations of tumor markers CEA and CA19-9 were reduced after treatment with probiotics, while the expression of interferon gamma (IFN-γ), interleukin-10(IL-10), and the count of CD4+ and CD8+ cells were upregulated upon intervention." (PMID 34992527, 2021). "Given that Th1 cells (CD4+ IFNγ+) play a key role in activating CD8+ T cells, we also analyzed the tumor-infiltrating CD4+ T cells." (PMID 34439144, 2021). "In addition to the tumor, the TdLNs also had significantly increased numbers of IFNγ-producing NK cells in the vanadyl sulfate plus NDV treatment group, suggesting that activated NK cells might be an important mediator of the antitumor efficacy of this therapy." (PMID 33614913, 2021). "Interferon-gamma (IFNγ) can enhance cytotoxic activities of natural killer cells and cytotoxic T lymphocytes (CTL), making tumor cells more prone to recognition and destruction." (PMID 34248641, 2021). "Upon exposure to IFNγ, chemokines CXCL9, CXCL10, and CXCL11 are produced by immune cells within the tumor, including macrophages and CD103+ DCs." (PMID 33816320, 2021). "In comparison, there is a modest increase in IL-12 production, and a substantial increase in IFNγ, CD4+ Th1 cells, and cytotoxic CD8+ T-cell levels, which makes the tumor micro-environment more favorable for responding to anti-PD-1 immunotherapy." (PMID 34267327, 2021).
tumor (continued). "Th1 cells secrete pro-inflammatory cytokines such as Interferon gamma (IFN-γ), IL-2, TNF-α, IL-8, and IL-1β and can have anti-tumor effects." (PMID 34290984, 2021). "In pancreatic cancer animal models, treatment with anti-CD40 agonist led to the recruitment of macrophages into the tumor and their polarization toward ECM-degrading cells by inducing the release of IFNγ and CCL2." (PMID 34831416, 2021). "Interferon-gamma (IFN-γ) and interleukin-2 (IL-2) expression in tumor tissue was much higher in mice treated with oxaliplatin with or without B. breve strains (B. bre JCM92 and B. bre Bb03) compared to IFN-γ and IL-2 expression in vehicle-treated mice." (PMID 33668827, 2021). "In the study, artemisinin was shown to significantly decrease TGF-β mRNA levels and populations of MDSCs and Treg cells within the tumor, while increasing TNF-α mRNA levels, CD4+ interferon gamma-expressed (IFN-γ+) T cells, and cytotoxic T lymphocytes." (PMID 34948368, 2021). "In tumor environment, it has been reported that AST decreased the amount of inflammatory markers such as TNF-α, IL-6, and IFNγ via NFk-B inhibition." (PMID 33509300, 2021). "However, given a dramatic prevalence of NK cells in blood compared to the tumor tissue, it is tempting to speculate that NK cells may primarily be responsible for the control of MHC-I deficient and IFNγ-resistant clones that make their way into the systemic circulation." (PMID 34201655, 2021). "Conversely, augmenting the IFNγ response pathway and the expression of HLA-I molecule enhances CTL-mediated anti-tumor immunity in many human cancers." (PMID 34458148, 2021). "There was also a significant difference between the SFV/IFNg+Pam3 and SFV/Luc+Pam3 groups (last day tumor volume p = 0.004 and tumor weight p = 0.004)." (PMID 34835178, 2021). "CD8+ T cells produce IFNγ, TNF and granzyme B by binding to T cell receptors and tumor cells, leading to tumor cell clearance." (PMID 34603277, 2021). "Overall, the combination of CD137, TNF, and IFNγ via intracellular detection was feasible and the use of CD137 improved the detection of tumor-specific reactive CD8+ TILs by more than 20% compared to the combination of TNF, IFNγ; and CD107a." (PMID 34707600, 2021). "Pharmacologic inhibition of RIP1 reprograms TAMs towards a MHCIIhiTNFα+IFNγ+ immunogenic phenotype in a STAT1-dependent manner, enhances cytotoxic T-cell activation, and impairs tumor growth in mice." (PMID 34201127, 2021). "In simplified terms, TAMs in a pro-inflammatory M1-like state can be recruited to the tumour site by cytokines such as interleukin 12 (IL-12), tumour necrosis factor (TNF), and interferon gamma (IFNγ) during early oncogenesis." (PMID 33659922, 2021). "Interferon-gamma (IFN-γ), as an important cytokine of the immune system to kill cancer cells, has been proved to induce tumor cell apoptosis or autophagy directly." (PMID 33712559, 2021). "Biomarkers, including CD8+ tumor infiltrating lymphocytes (TIL) and interferon-gamma (IFNg) gene expression profile (GEP), were measured in baseline tumor biopsies and analyzed for correlation with ORR and PFS." (PMID 33757523, 2021). "In the tumor-draining lymph nodes, antitumor immunity is driven by CCL3-dependent interferon gamma (IFNγ) production and CCL3-induced dendritic cells maturation." (PMID 36046113, 2021). "STAT3 plays a central role in neutrophil biology by regulating the production of inflammatory cytokines (e.g., IL1, IFNγ, TNF), while STAT3 inhibition in neutrophils enhances their cytolytic activity and promotes tumor regression." (PMID 34944848, 2021). "The results showed that TNFα, IL8, IFNγ, and GM-CSF were the most abundant pro-inflammatory cytokines secreted by CAR-T cells upon tumor engagement in a T:E ratio-dependent manner." (PMID 34093519, 2021). "At 6 days from the tumor injection, human astrocytes are defined by JAK/STAT pathway activation, an increased expression of CD274+, IL-10, and IFNγ secretion." (PMID 33804873, 2021).
tumor (continued). "In IECs, expression of STAT1 gene was also predicted to be upregulated by inflammatory cytokines IL1β and IFNγ and growth factor FGF7 identified as key molecules involved in tumor microenvironment." (PMID 34946170, 2021). "Infiltration of IFNγ-releasing CD8+ cytotoxic T cells and CD4+ helper T cells in the tumor environment was noticeably induced after rSmeg-hMIF-hIL-7 administration compared with Smeg administration." (PMID 34389619, 2021). "For example: interferon-gamma (IFNγ) released by CD8+ T cells can down-regulate the expression of SLC3A2 and SLC7A1 in tumor cells, inhibiting the uptake of cystine, limiting tumor development and improving patient prognosis." (PMID 34869390, 2021). "While CD8+ T cells are often determinant for tumor eradication, proper signals in the TME are often required to support their effector function, such as IFNγ and IL-1259." (PMID 34446712, 2021). "In vitro culture of NK cells, isolated from blood or tumor in human HCC, with autologous M-MDSCs (CD14+ HLA-DR-/low) significantly reduces the cytotoxicity and release of IFNγ in NK cells." (PMID 34557407, 2021). "I-E TIMEs are considered to be immunologically ‘cold’ since CTLs in them have low expression of activation markers granzyme B and IFNG and they have poor CTL infiltration into the tumour core." (PMID 34771746, 2021). "Moreover, anti-tumor necrosis factor alpha and anti-IFNγ treatment counteracted the reduced tumor growth that was observed after the decrease in FAP+ cells, suggesting that FAP may inhibit the production of tumor necrosis factor alpha and IFNγ or weaken the cellular response to these cytokines." (PMID 34490078, 2021). "While loss of MHC class I and II expression may reflect alterations in antigen processing in tumor or professional antigen presenting cells, it could also simply reflect a general reduced immune infiltration into the tumor, especially in the possible reduction of IFNγ." (PMID 33560598, 2021). "Consistently, the results of HE staining of tumor sections confirm the anti-angiogenesis function of T317 or D-Nap-GFFY-T317 in tumor microenvironment, which is also in an IFNγ-dependent manner." (PMID 33456564, 2021). "During interaction between tumor cells and ATC, several pro-inflammatory cytokines (IFNγ, TNF-α, IL-4, and IL-2) are released in the tumor microenvironment resulting in immunomodulation of the tumor cells, with upregulation of PD-L1expression on their surface." (PMID 34689789, 2021). "Exosomes isolated from non-small-cell lung cancer (NSCLC) patients reduced IFNγ and IL-2 production and induced apoptosis in CD8+ T cells, favoring tumor growth." (PMID 34065396, 2021). "In fact, the upregulation and secretion of chemotactic cytokines (such as IFNγ and TNF-α) increase the recruitment of additional immune cells and alter the tumor microenvironment, stimulating the inhibition of immune exclusion of cancer signatures." (PMID 34638337, 2021). "Assigning causality to the positive correlation between an immune-rich TME, inflammatory macrophage metagene signatures, high IFNγ-induced immune NAMPT expression, and tumor control will require further investigation." (PMID 33976173, 2021). "Our analysis revealed that IFNγ induces a selective and significant expression of CXCL10 in tumor cells." (PMID 33406104, 2021). "As IFNγ is secreted by macrophages and CD4+ and CD8+ T lymphocytes in the tumor microenvironment, it was conceivable that CD74 overexpression in solid tumors, and prognostic value, is simply a reflection of the level of immune infiltration." (PMID 34944801, 2021). "CD8+ T cells enhance ferroptosis of tumor cells through releasing interferon gamma (IFNγ) and repressing the expression of SLC3A2 and SLC7A11 in tumor cells." (PMID 34733403, 2021).